F8 (coagulation factor VIII)
Description:
Factor VIII, along with calcium and phospholipid, acts as a cofactor for F9/factor IXa when it converts F10/factor X to the activated form, factor Xa.
Synonyms: AHF; F8C; FVIII; DXS1253E; HEMA; F8B; THPH13
Tractability: Small molecule: a structure with a bound ligand is known; it has a binding pocket of medium quality. Antibody: a drug acting on it is in phase 2 or 3 trials; its Gene Ontology location is reachable by antibodies, with high confidence; UniProt places it where antibodies can reach, with medium confidence; UniProt predicts a signal peptide or a membrane-spanning region. PROTAC: a small molecule that binds it is known. Other modalities: an approved drug acts on it.
Target class: Secreted protein
Gene: Protein-coding gene on chromosome X (154,835,788 to 155,026,940, reverse strand). Ensembl gene ENSG00000185010.
Subcellular location: Secreted, extracellular space
Pathways (Reactome):
Disease: Defective F8 accelerates dissociation of the A2 domain; Defective F8 binding to the cell membrane; Defective F8 binding to von Willebrand factor; Defective F8 cleavage by thrombin; Defective F8 secretion; Defective F8 sulfation at Y1699; Defective F9 variant does not activate FX; Defective cofactor function of FVIIIa variant; Defective factor IX causes thrombophilia
Hemostasis: Amplification and propagation of coagulation cascade; Initiation of coagulation cascade; Platelet degranulation; Regulation of clotting cascade
Vesicle-mediated transport: COPII-mediated vesicle transport; Cargo concentration in the ER
Metabolism of proteins: Gamma carboxylation, hypusinylation, hydroxylation, and arylsulfatase activation
Gene Ontology:
Molecular function: protein binding; copper ion binding; oxidoreductase activity
Biological process: blood coagulation; blood coagulation, intrinsic pathway
Cellular component: COPII-coated ER to Golgi transport vesicle; endoplasmic reticulum lumen; endoplasmic reticulum-Golgi intermediate compartment membrane; extracellular region; Golgi lumen; plasma membrane; platelet alpha granule lumen
Gene-disease validity (ClinGen):
ClinGen rates the evidence that F8 causes each of these diseases.
hemophilia A (X-linked): Definitive. The most common form of hemophilia characterized by spontaneous or prolonged hemorrhages due to factor VIII deficiency.
Homologues: Orthologues: chimpanzee F8 (99% identical), macaque F8 (95% identical), rabbit F8 (79% identical), dog F8 (77% identical), guinea pig F8 (76% identical), mouse F8 (73% identical), pig F8 (67% identical), rat F8 (54% identical). Paralogues in human: F5 (27% identical), HEPHL1 (17% identical), HEPH (17% identical), CP (15% identical), CUBN (8% identical), CNTNAP5 (8% identical), CNTNAP2 (8% identical), CNTNAP4 (8% identical), CNTNAP3 (7% identical), NRXN2 (7% identical), CNTNAP3B (7% identical), NRXN3 (7% identical), and 23 more.
Diseases named in the same sentence as F8 in open-access papers:
F8 is named in the same sentence as 249 diseases in open-access papers, as found by Europe PMC text mining. Sharing a sentence is not in itself a finding about the gene and the disease. The quoted sentences say what the papers report.
hemophilia A (686 papers, 2007 to 2026). "Hemophilia is an X-linked recessive bleeding disorder caused by a deficiency of coagulation factor VIII (hemophilia A) or factor IX (hemophilia B)." (PMID 42078236, 2026). "Hemophilia A, an X‐linked, congenital, inherited bleeding disorder, is characterized by deficient coagulation factor VIII (FVIII)." (PMID 41122986, 2026). "The condition is primarily categorized into two clinical entities: hemophilia A, associated with mutations in the F8 gene encoding coagulation factor VIII, and hemophilia B, resulting from pathogenic variants in the F9 gene responsible for factor IX synthesis." (PMID 41153417, 2025). "F8 is an important component of the coagulation system, and its deficiency can lead to hemophilia A. Expression of FVIII activates the endoplasmic reticulum (ER) stress response, leading to oxidative stress and inducing apoptosis." (PMID 41188339, 2025). "It is an X-linked recessive condition, predominantly affecting males, and arises due to the deficiency of coagulation factor VIII (hemophilia A) or factor IX (hemophilia B)." (PMID 39998014, 2025). "The therapeutic mRNA encoded functional Factor VIII (FVIII), aiming to restore protein expression in hemophilia A, a genetic disorder caused by mutations or deficiencies in the F8 gene that results in the absence or dysfunction of FVIII protein." (PMID 40859956, 2025). "Hemophilia A is an inherited bleeding disorder that causes a deficiency in the coagulation factor VIII." (PMID 39821376, 2025). "Hemophilia A is a rare X-linked recessive bleeding disorder characterized by coagulation factor VIII (FVIII) deficiency or dysfunction." (PMID 40755915, 2025). "Gene therapy for hemophilia A primarily employs adeno-associated viral (AAV) vectors to deliver the F8 transgene—most commonly in the B-domain-deleted (BDD-FVIII) form—directly to hepatocytes." (PMID 41153417, 2025). "Hemophilia A is an inherited bleeding disorder resulting from the deficiency of coagulation factor VIII." (PMID 40388523, 2025). "Recently, peptide immunotherapy has been tested in preclinical models of hemophilia A (HA), which is an X-linked genetic disorder caused by mutations of coagulation factor VIII (FVIII)." (PMID 40276034, 2025). "Acquired hemophilia A (AHA) is a rare but potentially life-threatening bleeding disorder caused by autoantibodies against coagulation factor VIII (FVIII)." (PMID 41426522, 2025). "Hemophilia A (HA) is a bleeding disorder caused by a deficiency of coagulation factor VIII (FVIII), resulting in life-threatening bleeding in severe cases." (PMID 40305178, 2025). "Hemophilia A, characterized by a deficiency in coagulation factor VIII, represents the most common severe inherited bleeding disorder." (PMID 40649878, 2025). "Hemophilia A (HA) is a genetic bleeding disorder caused by the deficiency or inactivity of coagulation factor VIII (FVIII)." (PMID 39851501, 2025). "Hemophilia is a rare hereditary X-linked recessive disease caused by deficient activity of coagulation factor VIII (FVIII) in hemophilia A (1:5000) and factor IX (FIX) in hemophilia B (1:30,000)." (PMID 40076794, 2025). "Missense mutations are the most prevalent alterations in genetic disorders such as hemophilia A (HA), which results from coagulation factor VIII (FVIII) deficiencies." (PMID 40305178, 2025). "Hemophilia A (HA) is a relatively common genetic bleeding disorder caused by various mutations in the coagulation factor VIII (FVIII) gene on chromosome X1." (PMID 39762408, 2025). "Hemophilia A is an X-linked chronic bleeding disorder due to deficiency of the coagulation factor VIII." (PMID 40156956, 2025). "Hemophilia A is a rare X-linked recessive bleeding disorder caused by a deficiency or dysfunction in coagulation factor VIII (FVIII)." (PMID 40755915, 2025). "Hemophilia A is a congenital disorder characterized by a deficiency of coagulation factor VIII (FVIII), leading to frequent bleeding." (PMID 39422843, 2024).
hemophilia A (continued). "Hemophilia A is a genetic disorder characterized by a deficiency in coagulation factor VIII (FVIII), resulting in frequent bleeding episodes, joint damage, and a well-documented risk of reduced bone mineral density (BMD)." (PMID 39767573, 2024). "Haemophilia A (HA) is an X-linked recessive bleeding disorder caused by lack or deficiency of coagulation factor VIII." (PMID 38880904, 2024). "Hemophilia A (HA) is an X-linked recessive congenital bleeding disorder with a deficiency of coagulation factor VIII (FVIII)." (PMID 38532451, 2024). "Hemophilia is an X-linked recessive disorder caused by the deficiency in coagulation factor VIII (FVIII; hemophilia A) or IX (FIX; hemophilia B)." (PMID 38646558, 2024). "Hemophilia A, or classic hemophilia, is a hereditary bleeding disorder characterized by spontaneous or prolonged hemorrhages due to a deficiency of coagulation factor VIII." (PMID 39768276, 2024). "Hemophilia type A (HA) is a rare X-linked hemorrhagic disorder characterized by a deficiency in coagulation factor VIII (FVIII)." (PMID 39594927, 2024). "Hemophilia A (HA) is an X-linked disorder characterized by the functional deficiency of coagulation factor VIII (FVIII) resulting from pathogenic variants in the FVIII gene (F8); it has a worldwide incidence of 1/5000 male births." (PMID 39459632, 2024). "Background/Objectives: Hemophilia A is an X-linked recessive illness produced by a deficiency of coagulation factor VIII." (PMID 39728001, 2024). "Hemophilia A is an X-linked inherited bleeding disorder in which functional coagulation factor VIII (FVIII) is deficient." (PMID 38455035, 2024). "Hemophilia A is an X-linked disorder characterized by quantitative deficiency of coagulation factor VIII (FVIII) caused by pathogenic variants in the factor 8 (F8) gene." (PMID 39202783, 2024). "Haemophilia A(HA) is an X-linked recessive bleeding disorder caused by lack or deficiency of coagulation factor VIII (FVIII) which is encoded by F8 gene, and often results in excessive bleeding and leads to musculoskeletal complications." (PMID 38880904, 2024). "Hemophilia A is a rare congenital bleeding disorder caused by a deficiency of functionally active coagulation factor VIII (FVIII)." (PMID 36902866, 2023). "Hemophilia is a rare X-linked recessive inherited bleeding disorder caused by mutations of the genes encoding coagulation factor VIII (FVIII) (hemophilia A) or IX (FIX) (hemophilia B)." (PMID 36598583, 2023). "Hemophilia-A (HA) is caused by X-linked factorVIII (FVIII) gene (F8) mutations and variable deficiencies in plasma FVIII coagulant activity (FVIII:C)." (PMID 37886476, 2023). "Hemophilia A (HA) is a rare bleeding disorder resulting from either deficiency or dysfunction of coagulation factor VIII (FVIII), caused by deleterious mutations in the F8 gene encoding FVIII (NM_000132.3)." (PMID 37511607, 2023). "Hemophilia A (HA) is a congenital X-chromosomal bleeding disorder characterized by a deficiency of coagulation factor VIII (FVIII)." (PMID 37236229, 2023). "Hemophilia is a rare, inherited bleeding disorder caused by a deficiency of coagulation factor VIII (FVIII) (in hemophilia A) or factor IX (in hemophilia B)." (PMID 37542281, 2023). "Almost half of severe hemophilia A (HA) patients have a F8 intron-22 inversion mutation (Int22Inv), which precludes expression of an intact, functional FVIII protein." (PMID 36936969, 2023). "Hemophilia is an X-linked, recessive inherited disease caused by a defect or deficiency of coagulation factor VIII (hemophilia A) or factor IX (hemophilia B)." (PMID 37978530, 2023). "Haemophilia A is a bleeding disorder caused by deficiency of coagulation factor VIII (FVIII) which leads to severe and repeated bleedings." (PMID 36882773, 2023).
hemophilia A (continued). "Hemophilia is an X-linked congenital bleeding disorder caused by a deficiency of coagulation factor VIII (FVIII) (in hemophilia A) or factor IX (FIX) (in hemophilia B) and is one of the most important hereditary conditions in Iraq." (PMID 38406788, 2023). "Hemophilia A (HA) is one of the most widespread, X-linked, inherited bleeding disorders, which results from defects in the F8 gene." (PMID 36833187, 2023). "Hemophilia A (HA) is an X chromosome-linked recessive hereditary bleeding disorder that is caused by a lack or reduced activity of coagulation factor VIII (FVIII)." (PMID 37711502, 2023). "Haemophilia A is a severe X‐linked recessive inherited bleeding disorder caused by a deficiency in coagulation factor VIII (FVIII), a critical protein secreted by liver endothelial cells that is involved in the blood coagulation cascade." (PMID 37199059, 2023). "Hemophilia A results from congenital or acquired impairment in coagulation factor VIII activity, most often via genetic mutations that reduce or eliminate factor VIII production." (PMID 37264009, 2023). "Hemophilia A (HA) is a common congenital X-linked bleeding disorder defined by a deficiency in plasma coagulation factor VIII (FVIII)." (PMID 37893540, 2023). "Hemophilia A is a rare congenital bleeding disorder caused by the deficiency of biologically active coagulation factor VIII (FVIII)." (PMID 36902866, 2023). "Hemophilia A (HA), a rare recessive X-linked bleeding disorder, is caused by either deficiency or dysfunction of coagulation factor VIII (FVIII) resulting from deleterious mutations in the F8 gene encoding FVIII." (PMID 37511607, 2023). "Haemophilia A is a hereditary disease generated by a genetic defect in the long arm of the X chromosome, causing a qualitative or quantitative deficiency of coagulation factor VIII in the case of haemophilia A." (PMID 36810557, 2023). "Hemophilia A is a hemorrhagic disorder caused by insufficient or inadequate coagulation factor VIII activity." (PMID 38248356, 2023). "Hemophilia A (HA) is an inherited bleeding disorder caused by the deficiency of coagulation factor VIII (FVIII)." (PMID 36340724, 2022). "For decades, the mainstay of hemophilia A treatment was the replacement of deficient coagulation factor VIII (FVIII) to restore hemostasis, control, and prevent bleeding events." (PMID 35893734, 2022). "Hemophilia A is a rare inherited bleeding disorder caused by the deficiency or dysfunction of coagulation factor VIII (FVIII)." (PMID 36389359, 2022). "Haemophilia A (HA) is an X-linked congenital bleeding disorder resulting from mutations in the gene encoding the coagulation factor VIII (FVIII)." (PMID 34775566, 2022). "In recent years, gene therapy for hemophilia A/B, which are directly caused by mutations in coagulation factor VIII/IX, has shown promising results." (PMID 35173619, 2022). "Acquired hemophilia A is a rare disorder caused by development of autoantibodies to coagulation factor VIII." (PMID 35501873, 2022). "Hemophilia A is a genetic disorder caused by mutations in the f8 gene that lead to deficient activity of coagulation factor VIII (FVIII)." (PMID 34421119, 2022). "Deficiency of coagulation factors in hemophiliacs is caused by a deficiency of coagulation factor VIII (FVIII) (hemophilia A) or coagulation factor IX (hemophilia B)." (PMID 35360269, 2022). "Patients with mutations in the F8 gene, encoding coagulation protein factor VIII (FVIII), have an X-linked bleeding disorder known as hemophilia A (HemA) and lack FVIII or functional FVIII protein." (PMID 36377659, 2022). "Hemophilia A and hemophilia B are X-linked recessive bleeding disorders caused by a deficiency or dysfunction of coagulation factor VIII (FVIII) or FIX, respectively." (PMID 35280975, 2022). "Haemophilia is a rare genetic disorder that results from various degrees of deficiency of coagulation factor VIII (haemophilia A), or factor IX (haemophilia B), with an X-linked transmission." (PMID 36611305, 2022).
hemophilia A (continued). "Hemophilia A is the most frequent subtype, characterized by the deficiency of coagulation factor VIII, while hemophilia B refers to a deficiency of coagulation factor IX." (PMID 36159250, 2022). "Hemophilia A is caused by the deficiency of coagulation factor VIII (FVIII), while hemophilia B is resulted from the deficiency of coagulation factor IX (FIX)." (PMID 35365158, 2022). "Acquired hemophilia A is a rare condition caused by autoantibodies against endogenous coagulation factor VIII, which results in spontaneous bleeding." (PMID 36060351, 2022). "Hemophilia A is a monogenic X-linked congenital or acquired coagulopathy caused by a mutation in the F8 gene, which codes for FVIII." (PMID 35955419, 2022). "Hemophilia A and B are rare and recessive X-linked congenital diseases, caused by deficiency in coagulation factor VIII (FVIII) or IX (FIX), affecting one newborn every 5000 or 25,000 male births, respectively." (PMID 36004917, 2022). "Hemophilia is the most common X-linked chronic bleeding diathesis, caused by the deficiency of coagulation factor VIII (FVIII) or factor IX (FIX) in hemophilia A and hemophilia B, respectively." (PMID 35740010, 2022). "Acquired hemophilia A is a rare disorder caused by the development of autoantibodies against coagulation factor VIII." (PMID 35501873, 2022). "Among the genetic risk factors also recognized as unmodifiable risks, specific FVIII gene (F8) mutations that are responsible for the occurrence of hemophilia A, such as large deletions and nonsense mutations, are strongly correlated with inhibitor formation." (PMID 35893734, 2022). "Hemophilia A is a severe bleeding disorder caused by the deficiency of functionally active coagulation factor VIII (FVIII)." (PMID 36389737, 2022). "Hemophilia A (HA) is the most common severe congenital bleeding disorder caused by a deficiency in blood coagulation factor VIII (fVIII) due to mutations in the F8 gene." (PMID 34141826, 2021). "Hemophilia A is a relatively rare hereditary coagulation disorder caused by a defective F8 gene resulting in a dysfunctional Factor VIII protein (FVIII)." (PMID 34035274, 2021). "Acquired hemophilia A is defined as an acquired severe bleeding tendency caused by autoantibody formation against coagulation factor VIII." (PMID 34095769, 2021). "Hemophilia A (HA) is an X-linked recessive congenital bleeding disorder caused by mutations in the factor VIII (FVIII) gene (F8) that leads to deficient blood coagulation." (PMID 33644070, 2021). "Hemophilia A is an X-linked recessive disorder that is caused by mutation to coagulation factor VIII (fVIII)." (PMID 34177966, 2021). "Hemophilia A is a monogenic disorder caused by a mutation in the factor VIII (F8) gene, which leads to a deficiency of the blood clotting factor VIII (FVIII)." (PMID 34199901, 2021). "Hemophilia A (HA) is a genetic X-linked severe bleeding disorder characterized by spontaneous or traumatic bleeding due to coagulation factor VIII (FVIII) deficiency." (PMID 34640320, 2021). "Hemophilia A is an X-linked inherited blood coagulation disorder caused by the production and circulation of defective coagulation factor VIII protein." (PMID 34135429, 2021). "Haemophilia A is an X-linked inherited bleeding disorder caused by a deficiency in coagulation factor VIII (FVIII)." (PMID 33846178, 2021). "Hemophilia A (HA), a common bleeding disorder caused by a deficiency of coagulation factor VIII (FVIII), has long been considered an attractive target for gene therapy studies." (PMID 34485274, 2021). "Hemophilia-A is a heterogeneous deficiency in bloodcoagulation factor VIII (FVIII), which causes increasedbleeding and this occurs approximately 1 in almost 5000-10000 male births." (PMID 34308578, 2021). "Hemophilia A (HA) is an X-linked coagulopathy that results from deficiency in functional coagulation factor VIII (FVIII) in circulation." (PMID 34447745, 2021).